MIR15B (microRNA 15b)
Synonyms: hsa-mir-15b; MIRN15B; miR-15b
Gene: MicroRNA gene on chromosome 3 (160,404,588 to 160,404,685, forward strand). Ensembl gene ENSG00000207779.
Gene Ontology:
Biological process: miRNA-mediated post-transcriptional gene silencing
Cellular component: RISC complex
Homologues: Orthologues: chimpanzee ptr-mir-15b (100% identical), macaque mml-mir-15b (99% identical), pig ssc-mir-15b (98% identical), rat Mir15b (96% identical), dog MIR15B (93% identical), mouse Mir15b (64% identical), tropical clawed frog xtr-mir-15b (61% identical), zebrafish mir15c (52% identical). Paralogues in human: MIR15A (48% identical), MIR195 (42% identical), MIR16-2 (40% identical).
Diseases named in the same sentence as MIR15B in open-access papers:
MIR15B is named in the same sentence as 3 diseases in open-access papers, as found by Europe PMC text mining. Sharing a sentence is not in itself a finding about the gene and the disease.
MIR15B shares sentences with these, for which no sentence is quoted: cancer (1 paper); Parkinson disease (1); tumor (1).